ITPR3 (inositol 1,4,5-trisphosphate receptor type 3)
Diseases named in the same sentence as ITPR3 in open-access papers (continued):
Sharing a sentence is not in itself a finding about the gene and the disease.
thyroid cancer (1 paper, 2015). "Among the BRAFV600E-specific differentially expressed 18 genes, there are two involved in the calcification of epithelial cells: SLC34A2 and ITPR3, with the latter not previously related to BRAF mutation or to thyroid cancer." (PMID 26625260, 2015).
cancer (43 papers, 2013 to 2026). A tumor composed of atypical neoplastic, often pleomorphic cells that invade other tissues. "Together, these results from multiple cohorts of cell lines and patient tumor samples support the cooperative roles of SMARCA4/2 in regulating ITPR3 and confirm reduced IP3R3 expression in SMARCA4/2-deficient cancers." (PMID 34518526, 2021). "Consequently, stimulation of ITPR3 expression through SMARCA2 reactivation by HDACi enhanced chemotherapy response in SMARCA4/2-deficient cancer cells." (PMID 34518526, 2021). "Because of the importance of ITPR3 to the immunity and development of immune-associated diseases, it is reasonable to speculate that ITPR3 genetic variants might participate in the cancer pathogenesis." (PMID 28036301, 2017). "Emerging evidence has indicated that ITPR1, ITPR2, and ITPR3 were universally dysregulated in many cancers." (PMID 35580861, 2022). "The following study showed that increased levels of ITPR3 give cancer cells a survival advantage over normal by consisting of apoptotic cell death." (PMID 35580861, 2022). "ITPR3, as a ubiquitous endoplasmic reticulum calcium channel protein, was reported to be involved in the development and progression of various types of cancer." (PMID 33573671, 2021). "We demonstrated that ITPR3 knockdown suppressed cancer stemness by decreasing the CD44 protein level." (PMID 33573671, 2021). "Tumorsphere formation assays and colony formation assays were conducted to evaluate the potential effect of ITPR3 on cancer stemness properties." (PMID 33573671, 2021). "The need for a constitutive Ca2+ transfer between ER and mitochondria has been reported in several human tumorigenic cell lines, and the relationship between ITPR3 expression or activity and cell survival is particularly critical in the case of cancer cells." (PMID 32916960, 2020). "The migration and invasion potential have been shown to be severely influenced by ITPR3 levels in other cancer cells." (PMID 32916960, 2020). "Inositol 1,4,5-triphosphate receptor type 3 (ITPR3) is essential for both immune activation and cancer pathogenesis." (PMID 28036301, 2017). "However, we found that CCL5-activated CCR1 preferentially recruited Gαi, which rarely affects the ERK kinase pathway, and that it inhibited STAT3 phosphorylation by upregulating ITPR3, which is essential for both immune activation and cancer pathogenesis." (PMID 36317881, 2022). "Until now, the effect of ITPR3 in human cancer has remained controversial and confusing." (PMID 33573671, 2021). "Meanwhile, ITPR3 maintained the cancer stemness phenotype by regulating CD44 expression." (PMID 33573671, 2021). "Our study provided proof-of-principle data supporting that HDACi may be a potential therapeutic strategy to stimulate ITPR3 transcription through SMARCA2 reactivation and sensitize SMARCA4/2-deficient cancers to chemotherapy." (PMID 34518526, 2021). "However, three recent studies have found that cancer cells can adapt to the upregulation of ITPR3 and depend on it, thus driving oncogenesis and malignant cell transformation." (PMID 33573671, 2021). "However, as a calcium channel regulatory protein between the ER and mitochondria, the biological effects and expression of ITPR3 in human cancer development and progression are still unclear, especially in BCa." (PMID 33573671, 2021). "From the results above, we hypothesize that the oncogenic effect of ITPR3 is partly attributed to the inhibition of ITPR1 and that the ratio of ITPR3/ITPR1 may determine the destiny of cancer cells which is consistent with the conjectures in the previous research." (PMID 33573671, 2021). "In cancer, the same genes are thus simultaneously correlated with MYOF and ITPR3, tending to show that MYOF and ITPR3 are involved in the same cellular pathways." (PMID 38368370, 2024).
cancer (continued). "For both cancer types, cell lines with low SMARCA4 expression (bottom quartile) also expressed lower levels of ITPR3 compared to the rest of cell lines with high SMARCA4 expression." (PMID 34518526, 2021). "Focusing on p16-negative cases, they showed that a multivariate logistic regression model comprising ITPR3, KMT2D, EMILIN1, and patient’s age can accurately predict second cancer occurrence with 88% sensitivity and 75% specificity." (PMID 34771648, 2021). "However, the associations of other genes used in our model with ICI efficacy have not been reported, although some of them have been found to play critical roles in cancer, such as COL5A2, FAT2, ITPR3, PCDH20, and UTRN." (PMID 35557959, 2022). "Exercise-based approaches have recently been shown to impact the rno-miRNA-regulated target cancer gene candidates ITPR3, SOCS6, ITGA6, and NKX2-1 as biomarkers for cancer prognosis in rheumatoid arthritis diagnoses in pristane-induced arthritis (PIA) rat models." (PMID 36012617, 2022). "Previous studies have failed to address the specific mechanism of ITPR3 oncogenic roles in a variety of cancers, which attracts our attention." (PMID 33573671, 2021). "Furthermore, we observed a significant positive correlation between ITPR3 and SMARCA2 in these ovarian (n = 11, r = 0.825) and lung (n = 48, r = 0.584) cancer cell lines with low SMARCA4 expression." (PMID 34518526, 2021). "ITPR3 and CSC markers such as CD44, SOX2 and OCT4 were enriched in BCa stem cells, which indicated that ITPR3 might play a vital role in maintaining the cancer stemness phenotype." (PMID 33573671, 2021). "Therefore, the direct correlation between STIM1 protein expression level and ITPR3 expression found here may explain the suggested correlation between STIM1 protein levels and proliferation and malignancy in cancer cells." (PMID 32916960, 2020).
tumor (29 papers, 2015 to 2026). "Of note, top genes with sex differences in expression within tumor tissues, namely ITPR3 and DNAJB13, show sex-dependent association with stage, which was replicated in TCGA series." (PMID 33527138, 2021). "Furthermore, ITPR3 silencing caused tumour suppressive effects via reducing cell proliferation, migration, and invasion, while overexpressed one increased these cell functions." (PMID 35580861, 2022). "The xenograft tumors grew more slowly after ITPR3 knockdown compared with the control, and the tumor weight was much lighter in the ITPR3-depleted group." (PMID 33573671, 2021). "Meanwhile, the expression of cell cycle-related genes such as E2F1, Cyclin D1, Cyclin B1, and CDK2 was also decreased after ITPR3 knockdown while P21, as a classical tumor suppressor gene was upregulated." (PMID 33573671, 2021). "ITPR3, as an oncogene, plays a critical role in promoting proliferation and metastasis and maintaining tumor stemness depending on NF-κB activation." (PMID 33573671, 2021). "Furthermore, IRGs associated with tumor progression, including PDGFA, ITPR3, SLPI, TICAM1, and GATA4, were identified." (PMID 36588538, 2022). "As a result, we found that ITPR1, ITPR2, and ITPR3 proteins may interact with tumor-promoting genes, such as PLCB1, PLCB2, PRKCA, and RGS21, which may partially explain its oncogene roles." (PMID 35580861, 2022). "A positive correlation of ITPR3 expression with tumor purity was observed." (PMID 36588538, 2022). "In our study, ITPR3 expression declined with a more advanced tumor grade and stage." (PMID 36588538, 2022). "Moreover, immunohistochemistry staining showed that ITPR3, CD44 and Ki-67 were weaker, while IKBa was stronger in ITPR3-silenced tumor tissues." (PMID 33573671, 2021). "The results showed that ITPR3 was not only significantly upregulated in BCa tissues compared with corresponding normal peritumor tissues but also positively correlated with clinicopathological stages (Ta-T4) and tumor invasion degree (NMIBC and MIBC)." (PMID 33573671, 2021). "Furthermore, HDACi can recover inositol 1,4,5-trisphosphate receptor type 3 (IP3R3) expression and enhance cisplatin sensitivity in SMARCA4/A2-deficent tumor cells." (PMID 38347129, 2024). "The expression of ITPR3 and SLPI had a positive and negative correlation with tumor purity, respectively." (PMID 36588538, 2022).
peripheral neuropathy (2 papers, 2025). A disorder affecting the peripheral nervous system. "In this study, we discovered a homozygous canine ITPR3 nonsense variant leading to amelogenesis imperfecta and peripheral neuropathy in Lancashire Heeler dogs." (PMID 39804930, 2025).
autosomal dominant disease (1 paper, 2025). Autosomal dominant form of disease. "Unlikely in the studied dogs, CMT1J is predominantly an autosomal dominant disease in humans, but a few patients with compound heterozygous ITPR3 mutations have been reported." (PMID 39804930, 2025).
brain disorder (1 paper, 2023). A disease affecting the brain or part of the brain. "Challenges ahead will be to investigate the roles and function of TGM1, TGM2, ATF3, RCN3, ORAI1, and ITPR3 in TBI as well as TBI-induced secondary brain disorders." (PMID 37645012, 2023).
ITPR3 also shares sentences with these, for which no sentence is quoted: Graves disease (3 papers); infection (3); systemic lupus erythematosus (3); B cell CLL (2); COVID-19 (2); insomnia (2); melanoma (2); type 2 diabetes mellitus (2); alopecia (1); Alzheimer disease (1); Ataxia (1); atherosclerosis (1); autism (1); biliary atresia (1); bowel cancer (1); breast tumors (1); cardiac hypertrophy (1); coronary artery aneurysm (1); cytomegalovirus infection (1); diffuse large B-cell lymphoma (1); ectodermal dysplasia (1); Gillespie syndrome (1); glioma (1); heart failure (1); hereditary spastic paraplegia (1); Hyperglycemia (1); hyperthyroidism (1); hypotrichosis (1); incontinentia pigmenti (1); invasive breast carcinoma (1).
A further 22 diseases each share a sentence with ITPR3 in 1 paper.